OR2F1 (olfactory receptor family 2 subfamily F member 1)
Description:
Odorant receptor.
Synonyms: OLF3; OR2F3; OR2F3P; OR2F4; OR2F5; OR7-140; OR7-139; OR14-60; 7M1-2
Tractability: Antibody: its Gene Ontology location is reachable by antibodies, with high confidence; UniProt places it where antibodies can reach, with medium confidence; UniProt predicts a signal peptide or a membrane-spanning region.
Gene: Protein-coding gene on chromosome 7 (143,954,844 to 143,997,312, forward strand). Ensembl gene ENSG00000213215.
Subcellular location: Cell membrane
Pathways (Reactome):
Sensory Perception: Expression and translocation of olfactory receptors; Olfactory Signaling Pathway
Gene Ontology:
Molecular function: olfactory receptor activity; G protein-coupled receptor activity
Biological process: detection of chemical stimulus involved in sensory perception of smell; signal transduction; G protein-coupled receptor signaling pathway
Cellular component: plasma membrane; membrane
Genetic constraint (gnomAD): Loss-of-function variants: 4 observed, 4.13 expected, observed/expected ratio (o/e) 0.97, 90% interval 0.46 to 1.82. That is too few expected variants to judge how well the gene tolerates losing a copy. Missense variants: 386 observed, 389.97 expected, observed/expected ratio (o/e) 0.99, 90% interval 0.91 to 1.08. Synonymous variants: 146 observed, 163.46 expected, observed/expected ratio (o/e) 0.89, 90% interval 0.78 to 1.02.
Homologues: Orthologues: chimpanzee OR2F1 (98% identical), macaque OR2F1 (92% identical), dog OR2F1D (87% identical), mouse Or2f1 (87% identical), dog OR2F1 (86% identical), rat Or2f1 (86% identical). Paralogues in human: OR2F2 (90% identical), OR2D3 (52% identical), OR2K2 (51% identical), OR2D2 (49% identical), OR13C4 (47% identical), OR13C9 (47% identical), OR13D1 (47% identical), OR2G6 (47% identical), OR13C8 (47% identical), OR2B6 (47% identical), OR2S2 (47% identical), OR13C3 (46% identical), and 80 more.
Diseases named in the same sentence as OR2F1 in open-access papers:
OR2F1 is named in the same sentence as 1 disease in open-access papers, as found by Europe PMC text mining. Sharing a sentence is not in itself a finding about the gene and the disease.
OR2F1 shares sentences with these, for which no sentence is quoted: depression (1 paper).